CCND1 (cyclin D1)
Diseases named in the same sentence as CCND1 in open-access papers (continued):
Sharing a sentence is not in itself a finding about the gene and the disease.
cancer (continued). "Cyclin D1 is a cell cycle regulator that promotes cell proliferation along with many other important functions that enhances cancer development." (PMID 24260413, 2013). "Taken together, SOX2 and the other SOX family members activate the expression of MYC and CCND1, perhaps bypassing the blocked ER-mediated mitogenesis by which cancer cell proliferation can be maintained." (PMID 24355041, 2013). "Clinical characteristics of patients with high cyclin D1 and low cyclin D1 expressing cancers are compared in Table IV." (PMID 24100924, 2013). "The combination therapy induced cell death, partially caspase-dependent, and decreased proliferating cancer cells, with decreased expression of c-Myc and cyclin D1 and increased expression of p21WAF1/Cip, indicating arrest of cell growth." (PMID 24244355, 2013). "High cyclin D1 expressing cancers were more like to be adenocarcinomas and were more likely to present with brain or soft-tissue metastases." (PMID 24100924, 2013). "The findings from our study provide mechanistic insights into the anti-cancer activity of P276-00 and its effect on CCND1/CDK4/P16/pRB/E2F signaling cascade in FaDu cells." (PMID 23414419, 2013). "The authors suggested that curcumin treatment inhibits cancer cell proliferation by inhibiting cyclin D1 mRNA and protein expression and increasing expression of p21 protein." (PMID 24024180, 2013). "Eight proliferation-associated genes including CCND1, CDK1, CDK6 and 26 apoptosis-regulating genes (e.g. SOCS3) were differently expressed between juvenile and cancer groups mostly supporting the pronounced cell growth in CRC." (PMID 24098334, 2013). "Cyclin D1 was identified as a biomarker by studying the mechanism of action of erlotinib using in vitro models as well as pre- and post-treatment cancer biopsies." (PMID 24100924, 2013). "MiR-15a and miR-16 are frequently deleted or down-regulated and these events inversely correlate with the expression of Cyclin D1 in cancer." (PMID 23991105, 2013). "Several signaling molecules have been reported to contribute to the increased invasion and proliferation properties of certain types of cancer; these include c-Myc, cyclin D1 and β-catenin." (PMID 24137437, 2013). "As a critical modulator of G1 to S transition, increased expression of Cyclin D1 in cancer cells resulted in an uncontrolled growth advantage." (PMID 23578185, 2013). "In the present study, the results showed downregulation of the Wnt pathway, along with a decrease in the levels of β-catenin and cyclin D1, making Huaier an attractive potential drug for cancer therapy." (PMID 23599758, 2013). "ART derivatives induce apoptosis in human cancer cell lines and simultaneously down-regulate proteins such as c-myc, cyclin D1, and survivin, which are known to be involved with oncogenesis, the cell cycle, and apoptotic resistance respectively." (PMID 23516601, 2013). "Previous studies have shown that miR-195 prevents cell proliferation and promotes apoptosis in diverse cancers by binding to the 3′-UTRs of mRNAs of Bcl-2 and Cyclin D1." (PMID 23451060, 2013). "Consistently, DSG3 over-expression and plakoglobin translocation was found in the cancer tissues, in concurrence with up-regulations of c-myc, cyclin D1 and MMP-7." (PMID 23737966, 2013). "Multivariate Cox regression analysis indicated that moderate and high expression (++/+++) of cyclin D1 in cancer cells independently predicted an improved postoperative prognosis (HR, 0.13; 95% CI, 0.02–0.96; P=0.045)." (PMID 24137339, 2013). "Next we observed the TNF effects on NF-κB-regulated proteins (COX-2, Cyclin D1, and c-Myc) involved in cancer cell proliferation." (PMID 23864892, 2013). "Moderate to high expression (++/+++) of cyclin D1 in cancer cells predicted an improved postoperative prognosis of RCC when compared with that of negative or weak expression (−/+) (P=0.015; Kaplan-Meier analysis and the log-rank test)." (PMID 24137339, 2013).
cancer (continued). "Restoration of miR-9-mediated down-regulation of cyclin D1 and Ets1 by transient transfection, rescued the cancer cells from decrease in proliferation, migration and invasion." (PMID 23383271, 2013). "Many studies have reported that cancers have increased expression of cyclins such as cyclin D1 and cyclin E, etc.." (PMID 23305095, 2013). "COX-2 and Cyclin D1 are overexpressed in a variety of cancers and mediate cancer cell proliferation, and c-Myc is also involved in cancer cell proliferation." (PMID 23864892, 2013). "The oncogenic growth factors such as cyclin D1 and c-myc are required for cancer cells to enter from G1 phase to S phase of the cell cycle, and their aberrant expression is commonly found in a variety of tumors." (PMID 23573150, 2013). "Despite its role in destabilizing cyclin D1 in physiological cells, inhibition of GSK3β decreases cyclin D1 expression in cancer cells." (PMID 23408967, 2013). "Many reports concerning cyclin D1 in senescence, refer in fact to a senescence-like state in the population of heterogeneous by nature cancer cells." (PMID 23383739, 2013). "While cyclin D1 is frequently dysregulated in cancer and is a marker for disease progression, the involvement of cyclin D2 in cancer is not as well characterized." (PMID 24009521, 2013). "Deregulated function of cyclin D1, often resulting from overexpression of the protein, has been documented in numerous human cancers, including HCC." (PMID 23383245, 2013). "Upon binding to the 3′UTR, HuR stabilizes the mRNAs coding for cyclins (cyclin D1, E1, A2, B1), favoring cell cycle progression and promoting proliferation of cancer cells." (PMID 22666083, 2012). "At the same time, Survivin possesses a capability to upregulate the expression of Cyclin D1 and ensures cancer cells to pass G1-S checkpoint fluently and obtain an ability of persistent proliferation." (PMID 23185410, 2012). "Cyclin D1 gene amplification and overexpression are observed in several types of human cancer including OSCC." (PMID 23151022, 2012). "Apoptosis induction was preceded by marked inhibition of IGF-1R, cyclin D1, β-catenin, and Notch-1 expression in pancreatic cells, but only IGF-1R, cyclin D1, and β-catenin in the cancer stem-like cells." (PMID 22570653, 2012). "Curcumin treatment inhibited cyclin D1 mRNA and protein expression suggesting that it inhibits cancer cell proliferation." (PMID 22363450, 2012). "The intracellular effector Erk is activated by FGFR signaling, and its inhibition correlated with an impairment of cancer growth, an increased p21 and a decreased cyclin D1 expression." (PMID 22761819, 2012). "Such hypoM affected cancer-related biological functions and genes relevant to NB pathogenesis such as CCND1." (PMID 23144874, 2012). "The mammalian homolog of Cln3, Cyclin D1, is an important regulator of the G1/S progression in normal cells and commonly deregulated in cancer." (PMID 23217712, 2012). "Cyclin D1 gene regulates cell cycle and plays an important role in the tumorigenesis of human cancers." (PMID 22336657, 2012). "Genetically engineered cyclin D1 over-expression targeted to the mammary epithelial cells of transgenic mice leads to development of preneoplasia in young mice followed by cancer development when mice are older than one year." (PMID 24575359, 2012).
cancer (continued). "Cyclin D1 has been shown to be overexpressed in many cancers including breast, head and neck, esophagus and prostate." (PMID 22470469, 2012). "Cyclin D1 is known to play a crucial role in the development of specific subtypes of human cancers and it can promote progression through the G1-S phase of the cell cycle." (PMID 23024755, 2012). "The 11q13 amplicon has a complex structure with up to four cores, covering many genes involved in cancer (for example CCND1 and EMS1)." (PMID 22912841, 2012). "Consistent with this, the expression of cyclin D1 and c-Myc, two down-stream target genes of Wnt signaling that can induce S phase entry in many cancer cell lines, was also decreased under the regulation of the short form of LEF-1 (data not shown)." (PMID 22639890, 2012). "Cyclin D1 is one of the most important proteins regulating the cell cycle, and related with the development of many cancers." (PMID 22319632, 2012). "Cyclin D1 is well-established human oncogene, frequently deregulated in cancer, playing a specific role in cancer phenotype characterization and disease progression." (PMID 22770229, 2012). "In the literature, there are conflicting reports about prognostic impact of cyclin D1 expression and clinical outcome of different cancers." (PMID 22770229, 2012). "In summary, we have shown that chrysin posses potent invitro anti-cancer activity by suppressing cell proliferation, inducing G1 cell cycle arrest with the upregulation of p21 and decrease in cyclin D1, cdk2 protein levels." (PMID 22591439, 2012). "Mice over-expressing cyclin D1 were crossed with CERM mice to determine if ERα and cyclin D1 would demonstrate cooperativity in vivo in the development of hyperplasia and cancer." (PMID 24575359, 2012). "Cyclin D1, a cell cycle protein, is a well-established human oncogene: A recent census concluded that there was substantial evidence for the involvement of cyclin D1 amplification and overexpression in cancers." (PMID 22949827, 2012). "High percentages of precancerous and cancer cells exhibit increased cyclin D1, antigen identified by monoclonal antibody (Ki67), proliferating cell nuclear antigen (PCNA), phosphorylated ERK1/2 and phosphorylated STAT5." (PMID 24575359, 2012). "The probable target genes that are amplified and/or overexpressed in different cancers have been reported to include CCND1, FGF4, PPFIA1, CTTN and ORAOV1." (PMID 22920630, 2012). "All of the cancers that developed were hormone receptor positive, including those that developed on tamoxifen, and all showed expression of nuclear-localized cyclin D1." (PMID 24575359, 2012). "Retinoblastoma (Rb) phosphorylation and cellular growth are promoted by the activation of cyclin D1 in numerous cancers." (PMID 22319632, 2012). "Several well-known cancer-associated genes (including ADAMTS9, CCND1, HIC1, etc.)exhibited consistently disrupted methylation and expression statuses in the majority of the bladder urothelium cancer samples." (PMID 22140553, 2011). "The over-expression of CCND1 has been shown to be associated with the up-regulation of the GST-π gene, increasing the sensitivity of a cancer cell line to etoposide." (PMID 21609475, 2011). "It is well known that cyclin D1 is important in the development and progression of numerous cancers." (PMID 21955589, 2011). "Our results showed that the Buxus extract has specific cytotoxic effects toward cancer cell lines by mainly inducing a decrease in cyclin D1." (PMID 21935420, 2011). "Previous research exhibited that curcumin suppressed NF-κB-regulated proteins control cancer cell progression and these include cyclin D1 and blocked the transactivation of AP-1 on the MET promoter." (PMID 21858220, 2011). "For many HPV- cancers, including HPV- HNCs, reduced p16 expression correlates with p16 promoter hypermethylation, whereas cyclin D1 overexpression is linked to gene amplification." (PMID 21447181, 2011).
cancer (continued). "One such example is overexpression of cyclin D1, which has been observed in many types of cancer including hematologic malignancies and various solid tumors." (PMID 21299897, 2011). "Components of this pathway, particularly RB, p16Ink4a, and cyclin D1, are frequently altered in human cancers to promote deregulated cellular proliferation." (PMID 21819631, 2011). "Kaplan-Meier analysis and Cox proportional hazards modeling were used to assess the effect of cyclin D1 expression on cancer-specific survival (CSS) in univariate and multivariate analysis, adjusted for established prognostic factors." (PMID 21888663, 2011). "Accumulation of Cyclin D1 in cancer can result in overcoming ubiquitin-mediated degradation through several distinct mechanisms." (PMID 21347341, 2011). "For example, CEBPB (NFIL6) is a principal effector of cyclin D1 activity in human cancer and an enhancer of e.g. IL-6 transcription, which plays an important role in the acute phase response." (PMID 21799770, 2011). "Cyclin D1 is a transcriptional target of Wnt/β-catenin signaling, and is critical for cancer cell proliferation." (PMID 22195040, 2011). "Mechanistic characterization revealed that NSC-743380 suppressed the phosphorylation of C-terminal domain of RNA polymerase II, induced JNK activation, inhibited JAK2/STAT3 phosphorylation and suppressed cyclin D1 expression in sensitive human cancer cells." (PMID 22174819, 2011). "In HPV+ cancers, p16 up-regulation and cyclin D1 down-regulation are thought to be a consequence of feedback loops from E7 inhibition of Rb activity." (PMID 21447181, 2011). "The predictive accuracy of RB1 status by the CCND1/CDKN2A ratio was examined with the original 30 cancer cell lines which were used to develop the RB1 gene signature as a training set." (PMID 21447152, 2011). "The cyclin D1 gene amplification has been observed in cancers of the breast, head and neck or larynx." (PMID 21347341, 2011). "The β-catenin/TCF complex binds cyclin D1 and c-myc promoters, and increases expression in carcinoma cells." (PMID 21970630, 2011). "We have found that the altered expression of cyclin D1, maspin and integrin-α6 in skin of transgenic mice provide, at least in part, the molecular bases of the increase in the malignant potential of carcinomas originated in skin of K5-IKKα Tg mice." (PMID 21755017, 2011). "The most commonly affected cyclin in cancer cells is cyclin D1, an important cell cycle regulator that plays a role in transition of the cell from the G1 phase to the S phase." (PMID 22069560, 2010). "Phenotypic effects on cell proliferation and death, as well as modulation of key cancer-signaling nodes, including cyclin D1, c-Myc, p-Src, and survivin, were observed." (PMID 20525379, 2010). "Cyclin D1 governs the transit through the G1 phase of the cell cycle and is amplified and/or over-expressed in a relevant proportion of human cancers, including NB." (PMID 21050441, 2010). "Clinical observations indicate that cyclin D1 overexpression in human cancers correlate with metastasis." (PMID 20459741, 2010). "Cyclin D1 is a key actor for the development and progression of various cancers including hematological malignancies." (PMID 20459741, 2010). "Together with its corresponding binding partner cyclin-dependent kinases, CDK4 and CKD6, Cyclin D1 acts as a crucial cell cycle regulator which has been regarded to take an important part in the development and progression of several cancers." (PMID 20105337, 2010). "It was presumed that cancer cells with higher expression of cyclin D1 have stronger capacity for metastasis and earlier occurrence of micro metastasis than those with lower expression of cyclin D1." (PMID 20704822, 2010).
cancer (continued). "Although both GSK-3β and cyclin D1 are known to be involved in cell cycle regulation, their relationship in cancer cells remains controversial." (PMID 20704706, 2010). "Another study found cancers with higher indexes of cyclin D1 expression have the stronger capacity to metastasize." (PMID 20704822, 2010). "Decreases in phosphorylated-Rb has been associated with the knockdowns of CCND1, specifically the loss of phosphorylation at Ser780 on Rb has been associated with CCND1/CCND3 proteolysis and growth arrest in cancer cells." (PMID 20113529, 2010). "We observed that after treating cells for 48 h with the SCD1 inhibitor, cancer cells exhibited a marked decrease in the content of both cyclin D1 and CDK6." (PMID 20613975, 2010). "The activation of canonical pathway allows β-catenin to accumulate in the cytosol and enter the nucleus and induces expression of Wnt target genes like c-Myc, N-Myc, and cyclin D1, many of which have been implicaticated in human cancers." (PMID 20334650, 2010). "Cyclin D1 activity is required for G1- S phase progression and the regulation of its expression and/or stability is often deregulated in cancer cells." (PMID 19903334, 2009). "As EGFR and its downstream target cyclin-D1 are involved in cancer development and possibly affected by the putative CCHCR1 pathways, we examined their expression in comparison to CCHCR1." (PMID 19551138, 2009). "In this study, we have observed that in contrast to the ATM selective inhibitor KU55933, ATM/ATR dual inhibitors such as caffeine and CGK733 can suppress cyclin D1 levels in cancer cell lines." (PMID 19903334, 2009). "The CCND1 promoter has a consensus lymphoid enhancer binding factor-1 binding site, and in some cancer models its expression is controlled by β-catenin/TCF activation." (PMID 19473496, 2009). "Several of the proteins that play important regulatory roles in cancer progression and apoptosis have short half-lives (e.g. cyclin D1 (∼25 min); c-Myc (∼25 min); myeloid cell leukemia-1 (Mcl-1) (∼40 min)." (PMID 19412536, 2009). "Exposure of human cancer cell lines to caffeine and CGK733 was associated with a rapid decline in cyclin D1 protein levels and a reduction in the levels of both phosphorylated and total retinoblastoma protein (RB)." (PMID 19903334, 2009). "Previously, we demonstrated that cyclin D1 is essential for the proliferation of MCF-7 cancer cells." (PMID 19903334, 2009). "These tumors are highly proliferative, ER-negative carcinomas, showing strong positivity for Tcf/β-catenin target genes, Myc and cyclin D1, with expression of both luminal and basal epithelial markers." (PMID 19197353, 2009). "In most cancer types cyclin D1 over-expression results from induction by oncogenic signals, rather than a clonal somatic mutation or rearrangement in the cyclin D1 gene." (PMID 18834508, 2008). "Among those genes, we found well-known oncogenes playing a critical role in cancer, such as Cyclin D1 (CCND1) and FOS." (PMID 19812777, 2008). "Aberrant cyclin D1 expression has been observed early in carcinogenesis, and overexpression of cyclin D1 was reported in several human cancers, including uterine cervix, ovary, breast, urinary bladder, endometrium, and skin." (PMID 18197291, 2008). "PPARδ is a downstream target of β-catenin/T cell factor-4, which is central incolon cancer pathogenesis and regulates other cancer-promoting genes like c-mycand cyclin D1." (PMID 18551186, 2008). "It has also been shown to inhibit cyclin D1 expression and proliferation of some cultured cancer cells." (PMID 19046439, 2008).